LPCAT1 (lysophosphatidylcholine acyltransferase 1)
Diseases named in the same sentence as LPCAT1 in open-access papers (continued):
Sharing a sentence is not in itself a finding about the gene and the disease.
melanoma (6 papers, 2016 to 2024). A malignant, usually aggressive tumor composed of atypical, neoplastic melanocytes. "LPCAT1 promotes melanoma cell growth in an Akt-dependent manner, and its knockdown leads to cell cycle arrest at the G1/S transition." (PMID 38921444, 2024). "Lysophosphatidylcholine acyltransferase 1 (LPCAT1), an essential enzyme in lipid remodeling that converts lysophosphatidylcholine into phosphatidylcholine, has been shown to promote melanoma proliferation." (PMID 38921444, 2024). "At the same time, PAF is also responsible for radioresistance; therefore, blocking the activity of LPCAT1 and other enzymes with LPCAT activity increases tumor sensitivity to radiotherapy, particularly in melanoma." (PMID 38893234, 2024). "In our results, we found that LPCAT1 and ATX were highly expressed in melanoma tissues and B16-F10 cancer cells, which is consistent with previous reports." (PMID 27991567, 2016). "Moreover, we found that lysophosphatidylcholine acyltransferase 1 (LPCAT1) and autotaxin (ATX) were highly expressed in melanoma, and FAE markedly down-regulated their expression." (PMID 27991567, 2016). "The up-regulation of LPCAT1 and ATX expression could be responsible for the decreased LysoPCs and increased PCs in the plasma of B16-F10 melanoma-bearing mice." (PMID 27991567, 2016). "Interestingly, in the 57,490,258–58,411,259 pb region of chromosome 21 associated with two traits (VM and VN), we found five candidate genes (LPCAT1, CLPTM1L, TERT, TRIP13, and BRD9), all of which were related to the main types of skin cancer, i.e., melanoma and cutaneous squamous cell carcinoma." (PMID 39199954, 2024). "Moreover, the expression of LPCAT1 and ATX in melanoma tissues and cancer cells were markedly inhibited by FAE treatment, suggesting that the regulation of glycerophospholipid metabolisms by FAE was through, at least partially, down-regulating LPCAT1 and ATX expression in cancer cells." (PMID 27991567, 2016).
cervical cancer (5 papers, 2020 to 2024). A primary or metastatic malignant neoplasm involving the cervix. "In particular, seven genes showed higher expression in cervical cancer and positively correlated with EMT scores, including CSRP2BP, LPCAT1, NAT14, CREBBP, MSL3, ATF2 and GNPNAT1." (PMID 37845756, 2023).
glioblastoma (5 papers, 2017 to 2024). The most malignant astrocytic tumor (WHO grade IV). "In a recent study of the effects of lysophosphatidylcholine acyltransferase 1 (LPCAT1) in glioblastoma cells, the increase of disaturated PC species, especially PC 32:0, was taken as evidence for the importance of such lipids and lipid rafts for oncogenic signaling." (PMID 32314087, 2020). "In particular, AGPAT5, AGPAT6/GPAT4, AGPAT8/ALCAT1/LCLAT1, AGPAT9/LPCAT1, and AGPAT11/LPCAT2 show higher expression in glioblastoma tumors than in healthy tissue." (PMID 37046844, 2023).
oral squamous cell carcinoma (5 papers, 2015 to 2022). "To date, LPCAT1 overexpression has been reported in clear cell renal cell carcinoma, oral squamous cell carcinoma, gastric cancer and breast cancer." (PMID 30791942, 2019). "Similarly, knockdown of LpCat1 showed not only cellular proliferation but also invasiveness and migration were both repressed in oral squamous cell carcinoma." (PMID 34178664, 2021).
colorectal adenocarcinoma (4 papers, 2017 to 2024). The most common type of colorectal carcinoma. "The upregulation of enzymes such as LPCAT1 has been reported in human colorectal adenocarcinoma and metastatic prostate cancer, suggesting the involvement of the LPC metabolism in cancer progression." (PMID 38273378, 2024).
emphysema (4 papers, 2024 to 2025). "LPCAT1 deficiency can promote pulmonary emphysema through apoptosis of alveolar epithelial cells, suggesting that LPCAT1 plays an important role in cell survival." (PMID 38725025, 2024). "It was observed that Lpcat1 knockout (KO) mice were more susceptible to porcine pancreatic elastase (PPE)-induced emphysema." (PMID 38921452, 2024). "Therefore, the protective effect of LPCAT1 on emphysema may be linked to the inhibition of apoptosis in alveolar type 2 (AEC2) cells." (PMID 38921452, 2024). "Lysophosphatidylcholine acyltransferase 1 (LPCAT1) and its protein product have been extensively investigated for their potential role in various lung diseases, including emphysema, fibrosis, pneumonia, and neonatal respiratory distress syndrome." (PMID 39871194, 2025). "In an emphysema model, lysophosphatidylcholine acyltransferase 1 (LPCAT1), an enzyme responsible for catalyzing surfactant lipid biosynthesis and expressed in type 2 alveolar epithelial cells, converts LPC to PC, thereby reducing LPC levels in the body." (PMID 38921452, 2024).
retinal degeneration (4 papers, 2016 to 2022). Degeneration of the retina. "Here, we demonstrated that the loss of Lpcat1 leads to an early onset of severe retinal degeneration, triggered by light stimulus–independent photoreceptor cell apoptosis." (PMID 35452679, 2022). "Since the accumulated cGMP-dependent increase in calcium ion influx triggers retinal degeneration in rd1 mice, the underlying mechanisms of retinal degeneration in Lpcat1 KO mice differ from those in PDE6β mutated mice (rd1)." (PMID 35452679, 2022). "We demonstrated that retinal degeneration in Lpcat1 KO mice was caused by apoptosis of photoreceptor cells, which occurs in a light-independent manner." (PMID 35452679, 2022). "To assess the cause of retinal degeneration in Lpcat1 KO mice, we visualized the apoptotic cells in the retina using terminal deoxynucleotidyl transferase dUTP nick-end labeling (TUNEL)." (PMID 35452679, 2022). "Retinal degeneration 11 (rd11) mice carry a mutation in the Lpcat1 gene, and are an excellent model of early-onset rapid retinal degeneration (RD)." (PMID 27228218, 2016). "Therefore, to investigate whether the loss of function of LPCAT1 causes retinal degeneration, we used mice genetically deleted for the Lpcat1 gene." (PMID 35452679, 2022). "From the transcriptomic analyses, we identified the apparent induction of FosB mRNA in the Lpcat1 KO retina during the progression of retinal degeneration." (PMID 35452679, 2022). "A previous study has shown that a frameshift mutation in the Lpcat1 gene in rd11 and B6-JR2845 mice leads to the spontaneous development of severe retinal degeneration." (PMID 35452679, 2022). "DPPC is mainly biosynthesized by LPC acyltransferase 1 (LPCAT1), the loss of which by mutation induces retinal degeneration." (PMID 28578316, 2017). "In summary, we presented a detailed analysis of Lpcat1 deletion–induced retinal degeneration." (PMID 35452679, 2022). "As rd1 mice show similar phenotypes to those of Lpcat1 KO, early-onset, and light-independent retinal degeneration, we assessed whether the altered membrane lipid composition in Lpcat1 KO photoreceptor cells leads to PDE6β dysfunction." (PMID 35452679, 2022). "The induction of Fosb in Lpcat1 KO retinas was slightly delayed from the onset of retinal degeneration, suggesting that it might be triggered by apoptosis of photoreceptor cells." (PMID 35452679, 2022). "Therefore, cell types that upregulate Fosb during retinal degeneration in Lpcat1 KO retinas will be clarified by single-cell RNA sequencing in a future study." (PMID 35452679, 2022). "As the onset of photoreceptor cell death was followed by the upregulation of Fosb in Lpcat1 KO mice, this might not be the cause of retinal degeneration." (PMID 35452679, 2022). "However, considering the role of FosB as a component of activator protein-1, a dimeric transcription factor involved in inflammation, angiogenesis, and apoptosis, our results suggest that Fosb inhibition may be involved in retinal degeneration in Lpcat1 KO mice." (PMID 35452679, 2022). "However, photoreceptor cell apoptosis was observed even in dark-reared Lpcat1 KO mice, suggesting that retinal degeneration in Lpcat1 KO mice was independent of light stimulation." (PMID 35452679, 2022). "Since our transcriptomic analyses showed no sign of increased ER stress in Lpcat1 photoreceptor cells, we postulated that the altered palmitoyl-CoA flux by Lpcat1 deletion might be related to retinal degeneration." (PMID 35452679, 2022).
colon cancer (3 papers, 2017 to 2021). "The LPCAT1, which converts LPC into PCs, is overexpressed in several cancers and is associated with colon cancer growth showed that LPCAT4 was overexpressed in CRC and contributes to PC (16:0/16:1) accumulation via the enhanced re-acylation of LPC." (PMID 29359123, 2017). "Overexpression of LPCAT1 has been found in several malignancies, such as colon cancer." (PMID 34148155, 2021). "In addition, analyzes from colon cancer cell lines have shown a significant growth advantage when overexpressing LPCAT1." (PMID 34148155, 2021).
cutaneous squamous cell carcinoma (3 papers, 2022 to 2024). "The lysophosphatidylcholine acyltransferase 1 (LPCAT1) gene was identified as a cancer promoter in cutaneous squamous cell carcinoma." (PMID 39199954, 2024). "In cutaneous squamous cell carcinoma, LPCAT1 promotes progression via the EGFR-mediated AKT/p38MAPK signaling pathways." (PMID 35399731, 2022). "LPCAT1 was found to contribute to cutaneous squamous cell carcinoma progression through EGFR-mediated protein kinase B and p38MAPK signaling pathways." (PMID 36307879, 2022).
esophageal adenocarcinoma (3 papers, 2016 to 2021). A malignant tumor with glandular differentiation arising predominantly from Barrett mucosa in the lower third of the esophagus. "LPCAT1 staining was increased in malignant as compared to benign esophageal tissue and was found in high intensity in 26.4% of 288 interpretable esophageal adenocarcinomas (EACs) and in 23.2% of 211 squamous cell carcinomas (ESCCs)." (PMID 34148155, 2021).
metastatic prostate carcinoma (3 papers, 2016 to 2024). A carcinoma that arises from the prostate gland and has spread to other anatomic sites. "The study showed a significant difference in LPCAT1 IHC mean scores among benign, malignant and metastatic prostate cancer groups." (PMID 27916803, 2016). "The metastatic prostate cancer group revealed the highest LPCAT1 IHC mean score." (PMID 27916803, 2016).
pancreatic cancer (3 papers, 2017 to 2026). "Elevation of LPCAT1 expression suppresses signaling, proliferation and colony formation of KRASG12D-expressing human pancreatic cancer cells, while promoting those of KRASG12C-expressing cells." (PMID 42303154, 2026).
acute myeloid leukemia (2 papers, 2021 to 2022). Acute myeloid leukemia (AML) is a group of neoplasms arising from precursor cells committed to the myeloid cell-line differentiation. "Increased copy number and expression of LPCAT1 have been found in breast cancer, acute myeloid leukemia, and colorectal cancer and are correlated with a poor prognosis." (PMID 35880567, 2022). "For example, the expression of LPCAT1 is significantly upregulated in newly diagnosed acute myeloid leukemia (AML) cases compared with healthy controls, and thus may serve as an independent prognostic and diagnostic indicator for AML." (PMID 35880567, 2022).
esophageal tumor (2 papers, 2021). "However, although there was a trend of increased LPCAT1 immunostaining in unfavorable esophageal tumor phenotype, LPCAT1 expression was not prognostically relevant." (PMID 34148155, 2021).
lung squamous cell carcinoma (2 papers, 2019 to 2021). "Moreover, the expression of LPCAT1 in LUAD was significantly higher than in normal lung tissues and in lung squamous cell carcinoma." (PMID 30791942, 2019).
neonatal respiratory distress syndrome (2 papers, 2025). "In accordance with our results, we identified a single report that studied the association of the LPCAT1 (rs9728; c.*1668T>C) variant with the risk of respiratory distress syndrome among Chinese preterm neonates." (PMID 41007798, 2025). "This research demonstrated a genetic association between the LPCAT1 (rs9728; c.*1668T>C) variant and respiratory distress syndrome among Egyptian preterm neonates." (PMID 41007798, 2025).
osteosarcoma (2 papers, 2021 to 2025). A usually aggressive malignant bone-forming mesenchymal neoplasm, predominantly affecting adolescents and young adults. "SOX2 and LPCAT1 are implicated in tumor progression, but their roles in osteosarcoma pathogenesis and cholesterol metabolism remain unclear." (PMID 41358198, 2025). "In conclusion, our study advances the understanding of osteosarcoma pathogenesis by identifying the SOX2/LPCAT1/cholesterol metabolism axis as a driver of tumor progression and metastasis." (PMID 41358198, 2025). "Through integrated analysis of clinical samples, molecular biology experiments, and animal models, we demonstrated that both SOX2 and LPCAT1 are significantly overexpressed in osteosarcoma tissues and cell lines compared to normal controls." (PMID 41358198, 2025). "LPCAT1 emerges from our study as a central player in osteosarcoma biology with multifaceted functions." (PMID 41358198, 2025). "To investigate the functional role of LPCAT1 in osteosarcoma, we overexpressed LPCAT1 in MG63 cells and silenced it in U2OS cells with two independent shRNAs." (PMID 41358198, 2025). "Clinically, the consistent upregulation of LPCAT1 across different osteosarcoma subtypes suggests its potential as a universal therapeutic target." (PMID 41358198, 2025). "Scatter plots of 20 matched patient pairs showed higher SOX2 and LPCAT1 mRNA in osteosarcoma tissues and adjacent normal tissues." (PMID 41358198, 2025). "SOX2 and LPCAT1 expression in osteosarcoma tissues and cell lines was assessed via qRT-PCR and Western blot." (PMID 41358198, 2025). "This study provides compelling evidence establishing the SOX2/LPCAT1/cholesterol metabolism axis as a novel molecular mechanism driving osteosarcoma progression and metastasis." (PMID 41358198, 2025). "Across cell models, qRT-PCR showed higher SOX2 and LPCAT1 transcripts in osteosarcoma lines (MG-63, 143B, U2OS, MNNG/HOS) than in the human osteoblastic line hFOB 1.19." (PMID 41358198, 2025). "This study is the first to report that SOX2 indirectly participates in cholesterol metabolism in osteosarcoma cells by transcriptionally regulating LPCAT1." (PMID 41358198, 2025). "In osteosarcoma, the functional role and regulatory mechanisms of LPCAT1 remain unexplored." (PMID 41358198, 2025). "While SOX2’s role in osteosarcoma is established, its impact on cholesterol metabolism via LPCAT1 remains unknown." (PMID 41358198, 2025). "We measured TC and FC levels in osteosarcoma cells following LPCAT1 modulation." (PMID 41358198, 2025). "The SOX2/LPCAT1 axis drives osteosarcoma progression by modulating cholesterol metabolism." (PMID 41358198, 2025). "Notably, LPCAT1 overexpression reversed the inhibitory effects of shSOX2 on osteosarcoma growth, metastasis, and cholesterol metabolism." (PMID 41358198, 2025). "Given the reliance of osteosarcoma on lipid metabolism, investigating LPCAT1’s contribution could uncover novel therapeutic targets." (PMID 41358198, 2025). "Therefore, we hypothesize that the SOX2/LPCAT1 axis drives osteosarcoma progression by reprogramming cholesterol metabolism, thereby enhancing malignancy and metastatic potential." (PMID 41358198, 2025). "LPCAT1 or SOX2 overexpression promoted malignant behaviors and cholesterol metabolism (free cholesterol/total cholesterol levels, SREBP1/INSIG1 expression) of osteosarcoma cells, while shSOX2 or shLPCAT1 did the opposite." (PMID 41358198, 2025).
retinal disease (2 papers, 2010 to 2022). "Since increasing evidence indicates that the dysregulation of FA metabolism is demonstrated to involve in the various retinal diseases, LPCAT1-dependent saturated FA metabolism may also be implicated in human retinal disorders." (PMID 35452679, 2022).
retinitis pigmentosa (2 papers, 2016 to 2018). Retinitis pigmentosa (RP) is an inherited retinal dystrophy leading to progressive loss of the photoreceptors and retinal pigment epithelium and resulting in blindness usually after several decades. "In North America and China, molecular screening of the Lpcat1 gene in patients with retinitis pigmentosa or leber congenital amaurosis was performed, but no disease-causing mutations in the Lpcat1 gene were identified so far." (PMID 27228218, 2016).
asthma (1 paper, 2025). "This study aimed to investigate the possible association of LPCAT1-rs8352 genetic variant (single nucleotide change C to G) with the onset and severity of pediatric asthma." (PMID 39871194, 2025). "The LPCAT1-rs8352 allele C is associated with pediatric asthma onset and severity." (PMID 39871194, 2025). "When comparing individuals with the LPCAT1-rs8352 GG + GC genotypes to those with the CC genotype within the BA group, the latter again demonstrated significantly more severe asthma (p = 0.003)." (PMID 39871194, 2025). "Within the BA group, comparing individuals with the LPCAT1-rs8352 GG genotype to those with the GC + CC genotypes, the latter showed significantly more severe asthma (p = 0.042)." (PMID 39871194, 2025).
bladder cancer (1 paper, 2023). "The upregulated expression of LPCAT1 could also predict a positive response to immunotherapy in patients with bladder cancer (p = 0.032)." (PMID 37662906, 2023).
COVID-19 (1 paper, 2021). A disease caused by infection with severe acute respiratory syndrome coronavirus 2. "Besides its potential contribution to the modulation of the immune response and inflammation, the upregulation LPCAT1 could potentially link to the high venous and arterial thromboembolism incidence observed in severe cases of COVID-19 patients (~30.7%)." (PMID 34262555, 2021).
demyelinating disease (1 paper, 2025). A broad group of disorders that affect the myelin sheaths that cover the neurons. "The expression pattern of LPCAT1 limits its application in the treatment of demyelinating diseases such as MS, but further studies of LPCAT1's functions in other neural cells may make it feasible." (PMID 39878319, 2025).
glioma (1 paper, 2022). A benign or malignant brain and spinal cord tumor that arises from glial cells (astrocytes, oligodendrocytes, ependymal cells). "In glioma cells, LPCAT1 induces the conversion of lysophosphatidylcholine from an unsaturated to a saturated state accompanying the remodeling of membrane lipids, resulting in the activation and recruitment of the EGFR pathway, which, in turn, further promotes the biosynthesis of LPCAT1." (PMID 35399731, 2022).
HCMV infection (1 paper, 2025). "We found that HCMV infection promotes the levels of LPCAT1, a member of the family of host lipogenic enzymes that convert LPC to PC." (PMID 40827916, 2025). "Of these, LPCAT1 is reported to generate saturated PCs like those increased by HCMV infection." (PMID 40827916, 2025).
helminth infection (1 paper, 2024). "Although there was no study on the biological function of LPCAT1 in the response of hosts to helminth infection, it is reportedly upregulated in several carcinomas and is associated with cancer cell proliferation and the alteration of lipid composition." (PMID 38725025, 2024).
Intraventricular hemorrhage (1 paper, 2025). Bleeding into the ventricles of the brain. "Moreover, they observed a statistically significant association between the LPCAT1 rs9728 polymorphism and intraventricular hemorrhage (IVH) among Chinese preterm neonates (p = 0.039)." (PMID 41007798, 2025).
lobular carcinomas (1 paper, 2019). "Moderate or strong LPCAT1 positivity was more common in cancers of no special type (NST) (46.2%) than in lobular carcinomas (25.9%; p<0.0001)." (PMID 31533087, 2019).
lymph node metastasis (1 paper, 2021). "The overexpression of LPCAT1 is associated with lymph node metastasis and poor prognosis in ESCC patients." (PMID 34518524, 2021).
memory impairment (1 paper, 2024). "This indicates that eEF2K affects ether lipid metabolism through Lpcat1, thereby playing a role in the process of learning and memory impairment caused by ACR." (PMID 39180059, 2024).